IL33 (interleukin 33)
Diseases named in the same sentence as IL33 in open-access papers (continued):
Sharing a sentence is not in itself a finding about the gene and the disease.
tumor (continued). "As IL-33/ST2L signaling is linked to promote Th2 effector functions, we further evaluated Th2-related cytokines in CT26 tumor-bearing mice." (PMID 29950152, 2018). "More recent studies showed that IL-33 is expressed by vascular endothelial cells and tumor cells in human CRC." (PMID 30205617, 2018). "In contrast, neutralizing IL-33 or ST2 by administration of antibodies remarkably inhibits tumor size and decreases the density of ST2 positive Tregs inside tumor masses in tumor-bearing mice." (PMID 30547011, 2018). "IHC data revealed an increased expression of IL-33-immunoreactivity (IR) and ST2-IR located in both ESCC cells and tumor stromal cells; which were associated with advanced clinicopathological features such as TNM stages and node involvement." (PMID 30559604, 2018). "IL-33 induced SEMFs to express components of the extracellular matrix and growth factors that contributed to tumor growth and development." (PMID 30205617, 2018). "These chemoattractants are secreted by the IL-33 expressing tumour, and have been previously shown to create a permissive environment for infiltration of the immune cells." (PMID 29440650, 2018). "IL-33 has been shown to be a promising biomarker in several types of cancer for tumor detection and as a predictor of prognosis and therapeutic response." (PMID 30416507, 2018). "And for the first time, we found that blocking of IL-33 or ST2L reduced thetumor size accompany by decreasing serum IL-10 level in CT26 tumor-bearing mice." (PMID 29950152, 2018). "To evaluate the proliferation modulating effects of recombinant IL-33 incubation and other administrated factors, we measured tumor growth, colony formation, cell viability, and the expression of Ki67 and proliferating cell nuclear antigen (PCNA)." (PMID 30119635, 2018). "In contrast, a number of reports have analyzed the effects of IL-33 on NK cell expansion and/or activation in tumor-bearing mice." (PMID 30483263, 2018). "IL-33 therefore appears as a pro-tumorigenic cytokine that can also limit tumor growth through the activation of antitumor immunity." (PMID 30416507, 2018). "It is important to point out that current literature is somewhat controversial regarding the role of IL-33 in tumour development." (PMID 29440650, 2018). "Studies in ST2−/− Balb/c mice provided evidence that IL-33/ST2 signaling plays an important role in tumor angiogenesis and necrosis." (PMID 30205617, 2018). "Some studies have shown a positive correlation between IL-33 expression in tumor tissue and a favorable prognosis in cancer patients." (PMID 30483263, 2018). "The down-regulation of IL-33 during the metastatic process ultimately decreases the functionality of HLA-I and reduces immune-surveillance favoring tumor development." (PMID 30416507, 2018). "Data from both human and experimental studies demonstrated that IL-33 inhibits host anti-tumor immunity, remodels tumor stroma and enhances angiogenesis, thereby promoting the development of CRC." (PMID 30547011, 2018). "In both cases, IL-33/ST2 signaling exerts its effect by potently remodeling the tumor microenvironment through recruitment of immune cells that secrete a diverse collection of molecules that enforce their impact on tumor phenotype." (PMID 30205617, 2018). "IL-33 also promoted significant changes in the expression of antimicrobial peptides, and antibiotic treatment of V33 ApcMin/+ mice abrogated the tumor promoting-effects of IL-33 in the colon." (PMID 30205617, 2018). "Taking together, the resulting changes in gene expression induced by IL-33 are able to modify the tumour microenvironment and to attract more innate and adaptive immune cells in order to orchestrate anti-tumour immune responses." (PMID 29440650, 2018). "The central role of IL-33, a member of the IL-1 family, in inducing tumor-promoting type 2 responses has recently gained attention." (PMID 30631327, 2018).
tumor (continued). "IL33 was also upregulated in the tumor tissues of C3H mice and its expression is associated with MST1R expression in higher MST1R expressing group." (PMID 29566670, 2018). "Treatment of IL-33 in tumor-bearing mice impairs the functional activity of NK cells and dendritic cells and influences macrophages to M2 polarization, thus, suppressing innate and adaptive anti-tumor immunity." (PMID 30631327, 2018). "Overexpression of IL-33 by transfection into NSCLC cells isolated from patients and treatment of human lung A549 cells with IL-33 enhanced tumor outgrowth, migration, invasion, and metastasis in an ST2-dependent manner." (PMID 30205617, 2018). "Whereas low levels of IL-33, combined with a dampened type 1 lymphocyte-mediated antitumor immune response, promotes tumor progression through Treg, MDSC, M2 and mast cells." (PMID 29499051, 2018). "Studies have also been conducted on the role of IL-33 in tumor cell invasion, migration, and proliferation, which is relevantly given the similarities in the behavior of tumor cells and trophoblast cells." (PMID 29736154, 2018). "In contrast, in a murine AML model, systemic IL-33 administration promoted DC activation and “licensing” for cross-priming of tumor-reactive CD8+ T cells." (PMID 30483263, 2018). "IL-33 in tumor microenvironment was crucial for the accumulation and function of myeloid-derived suppressor cells." (PMID 29568370, 2018). "Systemic administration of IL-6 in the CCA murine model induced tumor development at a similar rate to IL-33." (PMID 30205617, 2018). "The increased number of immune cells in IL-33 expressing tumours was observed in mouse and in human tumour tissues." (PMID 29440650, 2018). "IL-33 also promotes tumor growth and metastasis by remodeling the tumor microenvironment (TME) and inducing angiogenesis." (PMID 30416507, 2018). "The data demonstrates increased numbers of CD4+ and CD8+ TILs, macrophages and neutrophils, within primary tumours or metastatic IL-33-expressing tumours when compared to metastatic tumours alone." (PMID 29440650, 2018). "By inoculating MC38 CRC cells in animals, we found the tumor growth in IL-33 transgenic mice was more rapidly than that in wild-type mice." (PMID 30119635, 2018). "We next analyzed the tumor-infiltrating lymphocytes (TILs) in B16-OVA tumor-bearing OT-II mice immunized with CurDCs plus IL-33." (PMID 30108595, 2018). "Overexpression of IL-33 in several tumor cell lines induced high numbers of ILC2s, when transplanted in mice, with potent anti-tumoral activity." (PMID 30483263, 2018). "The analysis demonstrated that both IL-33-IR positive or ST2-IR positive ESCC tumor cells and stromal cells had a high proliferative rate." (PMID 30559604, 2018). "The frequency of ILC2s isolated from lymph nodes of mice transplanted with RORα−/− BM bearing IL-33-expressing tumours was less than 0.05% of total cells isolated, and further served as a control for the efficiency of bone marrow transplantation." (PMID 29440650, 2018). "IL-33 was proved to be a robust inducer of T helper 2 cells (releasing cytokines like IL-4/5/6/10/13) in tumor microenvironment, but a suppressor to the secretion of T helper 1 cells (cytokines like IL-12, IFN-γ)." (PMID 30619376, 2018). "On the other hand, the number of suppressor T cells (FoxP3+) was higher in the tumor beds of A9+vector as compared to A9+IL-33." (PMID 30205617, 2018). "This implies that the presence of IL-33 in the tumour microenvironment increases the ILC2 frequency and activity in the tissue of the mice transplanted with WT BM, affecting the tumour growth rate accordingly." (PMID 29440650, 2018). "High levels of IL-33 in the tumor tissue can drive anti-tumor responses via CD8+ T cells, NK cells, NKT cells and DC." (PMID 29499051, 2018). "Transgenic host or tumoral expression or IL-33 administration inhibits tumor growth and pulmonary metastasis, via stimulation of NK, CD8+ T cells, DCs, ILC2s, and eosinophils." (PMID 30483263, 2018).
tumor (continued). "Previous studies showed IL-33 modulated tumor progression indirectly by regulating tumor stroma cells." (PMID 30119635, 2018). "When depleting CD8(+) T cells and NK cells, pulmonary metastasis was significantly increased, indicating that IL-33 can mediate the anti-tumor immunity of CD8(+) T cells and NK cells." (PMID 30619376, 2018). "There is increasing evidence that the IL-33/sST2 axis plays a crucial role in tumorigenesis and tumor progression in various malignancies such as colon, head and neck, breast, gastric, ovarian, lung, renal and pancreas." (PMID 30426271, 2018). "Recently, IL-33 was shown to be correlated with a bad prognosis in several types of cancer, although in some cases IL-33 behaves as a tumor suppressor by inducing an immune response." (PMID 30416507, 2018). "Our results showed that there were only 27 (56.2%) adenocarcinoma patients with high expression levels (++, intensity score: 5–7) of IL-33 in tumor tissues, while 43 (89.6%) adjacent normal tissues had high expression levels of IL-33." (PMID 29499051, 2018). "Collectively, these data indicate that cytokine production is affected by the IL33/ST2 axis during the anti-tumor immune response." (PMID 30112116, 2018). "Therapeutically delivery of IL-33 protein can inhibit the growth of established tumor by inducing robust anti-tumor immunity of CD8+ T cells." (PMID 29499051, 2018). "Currently, IL-33 is a possible inducer and prognostic marker of cancer development with a direct effect on tumor cells promoting tumorigenesis, proliferation, survival, and metastasis." (PMID 30416507, 2018). "In ApcMin/+ mice, epithelial-derived IL-33 promoted the expansion of ST2+ Treg cells in the colon correlating with increased tumor burden." (PMID 30483263, 2018). "The minute amount of extracellular IL-33 promotes tumor growth through recruiting MDSC but cannot have any significant effect on type 1 lymphocytes, likely due to differential expression of ST2 on MDSC and CD8+ T cells." (PMID 29499051, 2018). "Conversely, other studies pointed out anti-cancer activities of IL-33 to inhibit tumor progression in cellular levels and animal models." (PMID 30619376, 2018). "Cytokines are central mediators between cells in the inflammatory tumor microenvironment, in which Interleukin-33 (IL-33) is considered as an alarmin released after cellular damage." (PMID 30619376, 2018). "Our findings indicate that the IL-33/ST2 pathway contributes to the development of SCC by affecting leukocyte migration to tumor microenvironment and impairing NK cytotoxic activity." (PMID 30112116, 2018). "Consistent with the result of the immunohistochemical staining, when we analyzed the mRNA level of 80 adenocarcinoma samples, we found that the mRNA level of IL-33 was significantly reduced in tumor tissues when compared to their adjacent normal tissues." (PMID 29499051, 2018). "IL-33 is able to promote inflammatory events which contribute to tumorigenesis whilst activating anti-tumor immune responses." (PMID 30416507, 2018). "In this model, IL-33 was mainly expressed in the tumor stroma and positively correlated with Lnc-CAF to increase the expression of the CAF markers α-SMA, vimentin, and cadherin." (PMID 30205617, 2018). "Administration and overexpression of IL-33 induced tumor sphere formation and protected cells from chemotherapy-induced apoptosis." (PMID 30205617, 2018). "In essence, pulmonary infection with gram-negative bacteria in NSCLC patients results in TLR4 activation and IL-33 overexpression, promoting tumor progression and recurrence by enhancing cancer metabolic reprograming and cancer stem cell properties." (PMID 29568370, 2018). "We and others have previously demonstrated that both IL-33 and ST2 are highly expressed in tumor-associated microvessels, implying autocrine stimulation of angiogenesis during the progression of CRC." (PMID 30547011, 2018).
tumor (continued). "IL-33 favors tumor progression through the immune system by inducing M2 macrophage polarization and tumor infiltration, and upon activation of immunosuppressive cells such as myeloid-derived suppressor cells (MDSC) or regulatory T cells." (PMID 30416507, 2018). "The primary TC1 tumour is a murine lung primary tumour model that we have previously shown to produce IL-33 and to express MHC-I on its surface." (PMID 29440650, 2018). "IL-33 in tumor tissues is down-regulated after transient high expression via innate immune regulation." (PMID 28402273, 2017). "The expression of IL33 in tumor tissues is depressed, but tumor stroma and serum have increased levels of IL33, suggesting the distinct functions of IL33 in cancer cells from the microenvironment." (PMID 29285217, 2017). "Since CRC associated IL-33 is predominantly nuclear, we also generated transgenic mice that expressed full-length IL-33 in the epithelium to test its role on the tumor development." (PMID 28710436, 2017). "To explore the in vivo relevance of above findings, we analyzed the correlation of IL-33 expression with Ki-67 proliferation index (PI), and expressions of arginase 1, IL-10 and FoxP3 in tumor tissues of NSCLC patients." (PMID 28978138, 2017). "Herein, we determined that interfere with IL-33 activity was an effective strategy for limiting NSCLC tumor growth using a preclinical model with human NSCLC xenografts." (PMID 28978138, 2017). "Analysis of a tumor tissue microarray of UC-CRC patients (n = 47) obtained from our MSSM Biorepository showed that there was expression of IL-33 in the epithelium in 9 out of 47 samples (19.2%)." (PMID 28710436, 2017). "Taken together these results confirm a positive role for IL-33 signaling in tumor development in the ApcMin/+ background." (PMID 28710436, 2017). "Taken together, our data indicate that IL-33 is expressed by tumor epithelial cells in approximately 30% of all samples (n = 89)." (PMID 28710436, 2017). "IL-33 promoted marked changes in the expression of antimicrobial peptides and antibiotic treatment of V33 ApcMin/+ mice abrogated the tumor promoting-effects of IL-33 in the colon." (PMID 28710436, 2017). "Tumour‐derived IL‐33 dramatically enhances neo‐angiogenesis by increasing endothelial cell proliferation, migration and differentiation into blood vessels to robustly increase metastatic spreading of CRC cells to the liver." (PMID 28085225, 2017). "Overexpression of IL-33 in tumor cells strongly inhibited tumor growth by increasing the numbers of tumor-infiltrating NK cells and CD8+ T cells, and their production of IFN-γ51." (PMID 28710436, 2017). "Tumor development results in downregulation of IL-33 in epithelial cells but upregulation of IL-33 in the tumor stroma and serum, so IL-33 levels in tissue or serum are different." (PMID 28402273, 2017). "We found that the expression of IL-33 mRNA was significantly increased throughout tumor development." (PMID 28710436, 2017). "IL-33 also promoted marked changes in the expression of antimicrobial peptides and antibiotic treatment of V33 ApcMin/+ mice abrogated the tumor promoting-effects of IL-33 in the colon." (PMID 28710436, 2017). "In essence, NSCLC-derived IL-33 supports tumor growth in an autocrine manner and educates immune surveillance in tumor microenvironments, favoring immune escape of tumor cells." (PMID 28978138, 2017). "Superior anti-tumour efficacy of artLCMV immunotherapy depends on interleukin-33 signalling, and a massive CTLeff influx triggers aninflammatory conversion of the tumour microenvironment." (PMID 28548102, 2017). "Since epithelium-expressed IL-33 promoted tumor growth not only in the LI but also in the SI, we also investigated the ST2+ Treg cells in the SI." (PMID 28710436, 2017). "To study the relevance of increased IL-33 expression to tumor development we generated IL-33 transgenic mice and mice deficient for its receptor (ST2)." (PMID 28710436, 2017).
tumor (continued). "The hypoxic environment of tumor also induces other modulators such as IL-10, IL-27, IL-33 and VEGF." (PMID 28758974, 2017). "Overall the down-regulation of IL-33 takes place concomitantly with the transition from primary to metastatic tumours and represents an entirely new form of tumour immune-escape." (PMID 27619158, 2016). "The present study indicates that complementation of tumour cells with IL-33 induces MHC-1 production and contributes to a reversal of antigen presentation deficiency, consequently shifting the tumour phenotype from immune evasiveness to immune recognition." (PMID 27619158, 2016). "Accordingly, administration of IL-33 in this model enhanced tumor cell proliferation in WT mice, through an indirect effect of IL-33 on tumor cells." (PMID 28119694, 2016). "A recent study shows that in a mouse breast cancer model, injection of IL-33 protein stimulates primary tumour growth and metastasis." (PMID 27150562, 2016). "We found that the Panc02 pancreatic xenograft tumour expressed endogenous IL-33 at a high level (>6,000 pg ml−1) as compared with other tumour types." (PMID 27150562, 2016). "The central role of IL-33 in inducing tumor-promoting type 2 responses has recently gained attention." (PMID 28536374, 2016). "It has been previously shown that IL-33/IL-33R axis suppressed innate anti-tumor immunity and apparently favored neoangiogenesis." (PMID 26919112, 2016). "Recent studies from transplantable solid tumor models have indicated a direct role of exogenous IL-33 in promoting antitumor CD8+ T cell immunity using either IL-33 transgenic mice, IL-33 DNA as vaccine adjuvant, or IL-33 expressing tumor cells." (PMID 27517629, 2016). "In another experimental setting, macrophages were stimulated with IL-33 protein in vitro before implantation with tumour cells in vivo." (PMID 27150562, 2016). "The proinflammatory interleukin-33 (IL-33) binds to its receptor ST2L on the surface of immune cells and stimulates the production of Th2 cytokines; however, the effects of IL-33 on tumour cells are poorly understood." (PMID 26775708, 2016). "Genetic propagation of T241 tumours with IL-33 by lentiviral approach led to overexpression of IL-33 protein in tumour tissues." (PMID 27150562, 2016). "We demonstrate that the expression of IL-33 plays a protective role during the transition from primary to metastatic tumours." (PMID 27619158, 2016). "IL-33 expression by the A9+IL-33 tumour cells reduced the average number of GFP-positive cells to ~0.15% in liver, and to ~2.63% in the adrenal glands." (PMID 27619158, 2016). "In contrast to our findings, a recent study shows that systemic injection of IL-33 stimulates primary tumour growth and metastasis in a mouse tumour model." (PMID 27150562, 2016). "As a result, IL-33 expression decreases the metastatic potential of the cancer cell population reducing the in vivo tumour growth rate, metastatic spread of the disease and its severity." (PMID 27619158, 2016). "This is in line with findings indicating that IL-33 increases the numbers of CD8+ T cells and NK cell-producing IFN-γ in transgenic B16 tumors overexpressing IL-33, thereby mediating a microenvironment favoring tumor rejection." (PMID 28119694, 2016). "To validate these findings in vivo, we analysed IL-33 protein expression in PDGF-BB+ T241 tumours and found a marked increase of IL-33 expression as compared with vector tumours." (PMID 27150562, 2016). "Further, overall IL-33 expression in tumor tissue during the observed period of time was significantly higher in WT mice (p = 0.022)." (PMID 26919112, 2016). "To our surprise, we detected IL-33 even in P29 tumours established in IL-33−/− mice, even though P29 cells hardly expressed IL-33 in vitro." (PMID 26775708, 2016). "IL-33 protein expression levels in A431 tumour grafts were markedly decreased by the Pdgfb-specific shRNA." (PMID 27150562, 2016).